RN7SL26P (RNA, 7SL, cytoplasmic 26, pseudogene)
Gene: Miscellaneous RNA gene on chromosome 6 (33,540,694 to 33,541,000, forward strand). Ensembl gene ENSG00000242014.
Homologues: Orthologues: chimpanzee Metazoa_SRP (98% identical), macaque Metazoa_SRP (92% identical), guinea pig Metazoa_SRP (56% identical). Paralogues in human: RN7SL1 (81% identical), RN7SL2 (81% identical), RN7SL3 (79% identical), RN7SL126P (79% identical), RN7SL45P (78% identical), RN7SL300P (77% identical), RN7SL709P (77% identical), RN7SL296P (77% identical), RN7SL444P (77% identical), RN7SL147P (76% identical), RN7SL732P (76% identical), RN7SL786P (76% identical), and 701 more.